HDAC11 (histone deacetylase 11)
Diseases named in the same sentence as HDAC11 in open-access papers (continued):
Sharing a sentence is not in itself a finding about the gene and the disease.
metabolic syndrome (5 papers, 2020 to 2025). A cluster of metabolic risk factors for CARDIOVASCULAR DISEASES and TYPE 2 DIABETES MELLITUS. "Genetic deletion of HDAC11 was found to attenuate DM-associated cardiac apoptosis, inflammation, and dyslipidemia by attenuating cardiac oxidative stress." (PMID 34071497, 2021). "HDAC11 depletion elevates blood pressure, reduces the inguinal fat-pad mass and body weight, with improved cardiac function, dyslipidemia, enhanced SOD activity." (PMID 36339432, 2022). "In addition, a fructose injury-induced mouse model of diabetic heart failure that lacks HDAC11 had lower levels of apoptosis, dyslipidemia, inflammation, and oxidative stress." (PMID 36339432, 2022). "Additionally, HDAC11 deletion has been reported to reduce dyslipidemia, oxidative stress, inflammation, and apoptosis in the heart of diabetic mice." (PMID 34071497, 2021).
prostate carcinoma (5 papers, 2021 to 2026). A carcinoma that arises from epithelial cells of the prostate gland. "HDAC11-deficient CAR-T cells (shD-NKG2D-CAR-T) displayed better cytotoxicity than wild-type CAR-T cells against prostate cancer cell lines." (PMID 38835760, 2024). "Here, we investigated the potential of HDAC11 downregulation using RNA interference in CAR-T cells to improve immunotherapeutic outcomes against prostate cancer." (PMID 38835760, 2024). "In contrast, modulation of HDAC11 does not alter AR splicing in prostate cancer cells, indicating cell type specific regulation." (PMID 42124652, 2026). "The findings suggest that HDAC11 knockdown holds promise as a strategy to enhance the therapeutic impact of CAR-T cells, with potential implications for improving patient outcomes in prostate cancer treatment." (PMID 38835760, 2024).
diabetes (4 papers, 2020 to 2025). "Collectively, the development of small molecules that suppress HDAC11 activity would be promising in treating diabetes and its associated complications." (PMID 33096729, 2020). "In the heart, HDAC11 deletion improved several parameters of diabetes mellitus-associated cardiac injury, including oxidative stress, apoptosis, inflammation and cardiac function, pointing to HDAC11 suppression as a potential therapeutic target for treating such a cardiac condition." (PMID 36901738, 2023). "In mice fed with high fat diet (HFD), HDAC11 deletion significantly decreases blood insulin levels, stabilizes blood glucose, and greatly reduces blood glucose levels after insulin challenge, thereby enhancing glucose tolerance and ameliorating diabetes." (PMID 36339432, 2022).
Hypercholesterolemia (4 papers, 2019 to 2025). An increased concentration of cholesterol in the blood. "Recent studies have indicated that HDAC, particularly HDAC11, is involved in adipogenesis regulation, with HDAC11‐deficient mice displaying hypercholesterolemia." (PMID 40060193, 2025). "HDAC11 deficiency enhances glucose tolerance and insulin sensitivity, attenuates liver damage, hepatosteatosis and hypercholesterolemia by boosting energy expenditure through promoting thermogenic capacity." (PMID 36339432, 2022). "In the context of metabolic regulation, HDAC11 has been directly associated with insulin sensitivity, glucose tolerance, hypercholesterolemia, and hepatosteatosis and liver damage since the depletion of HDAC11 attenuated these effects." (PMID 31067680, 2019). "Importantly, HDAC11-deficient mice show alleviated hypercholesterolemia, hepatic steatosis and liver damage." (PMID 36339432, 2022).
lung adenocarcinoma (4 papers, 2016 to 2023). A carcinoma that arises from the lung and is characterized by the presence of malignant glandular epithelial cells. "Our study presents a novel role of HDAC11 in lung adenocarcinoma progression and the potential use of highly selective inhibitors of HDAC11 in combating lung cancers." (PMID 32170113, 2020). "In conclusion, this study presents a mechanistic basis for the role of HDAC11 in lung adenocarcinoma and suggests that once the parameters for in vivo studies and efficacy are met, they would be of immense potential in combating NSCLC." (PMID 32170113, 2020). "Additional multivariate analysis of the data showed poor survival in early stage (Stage 1) lung adenocarcinoma patients with higher expression of HDAC11." (PMID 32170113, 2020). "We found that the HDAC11 levels were elevated by ~2.5 fold in the lung adenocarcinoma as well as in squamous cell carcinoma as compared to normal lung tissue." (PMID 32170113, 2020). "At most, the gene expression of a histone demethylase, KDM5D, and a histone deacetylase, HDAC11, was considerably decreased among 18 and 4 lung adenocarcinoma cell lines, respectively." (PMID 27042856, 2016). "Also, it was found that higher expression of HDAC11 in male lung adenocarcinoma patients correlated with poor survival." (PMID 32170113, 2020).
atherosclerosis (3 papers, 2021 to 2025). A disease characterized by the build-up of fatty material and calcium deposition in the arterial wall resulting in partial or complete occlusion of the arterial lumen. "Of note, HDAC11 is the only member of Class IV that has been least explored and analyzed in the development of atherosclerosis in humans and animals." (PMID 38001953, 2023). "Hence, these findings determine the dysfunction of HDAC11 in the pathogenesis of atherosclerosis and CAD, which must be further studied in detail." (PMID 38001953, 2023). "This suggests that HDAC11 may be involved in the process of PAR2 in promoting atherosclerosis." (PMID 40497340, 2025).
glioblastoma (3 papers, 2008 to 2022). The most malignant astrocytic tumor (WHO grade IV). "HDAC11, the only member of class IV, had the lowest median value for normal brain tissue (3.67) and the highest for glioblastoma (1.02)." (PMID 18713462, 2008).
lung carcinoma (3 papers, 2020 to 2024). "Our results show the role of HDAC11 in regulating Sox2 expression in lung cancer cells, with a limited effect on Oct4 and Nanog expression." (PMID 32170113, 2020). "The effectiveness of the HDAC11 inhibitors against the TKI resistant lung cancer cell lines shows a potential of such inhibitors to be used in patients with TKI resistance." (PMID 32170113, 2020). "Next, we assessed if expression of HDAC11 correlated with the expression of Sox2 in the tissues of lung cancer patients." (PMID 32170113, 2020). "An immunohistochemical analysis was carried out on human tissue microarrays to assess whether the levels of HDAC11 were altered in lung cancer." (PMID 32170113, 2020). "The expression pattern of HDAC11 in lung cancer cell lines was next examined." (PMID 32170113, 2020). "Our finding that the novel HDAC11 inhibitors described here can eliminate the self-renewal of stem-like cells and can target even drug resistant lung cancer cells suggest that these novel agents and their derivatives would be of potentially useful in combating NSCLC." (PMID 32170113, 2020). "Since we found an increase in HDAC11 expression in lung cancer, we examined whether the expression of HDAC11 predicts the prognosis of lung cancer patients." (PMID 32170113, 2020). "In addition, we have used highly selective HDAC11 inhibitors that not only target stemness and adherence independent growth of lung cancer cells but these inhibitors could also efficiently ablate the growth of drug-insensitive stem-like cells as well as therapy resistant lung cancer cells." (PMID 32170113, 2020). "Towards this purpose, we labelled A549 or H1650 lung cancer cell lines with CellTracker red dye and the CAFs with CellTracker green dye and co-cultured them on tissue culture plates in the presence or absence of HDAC11 inhibitors." (PMID 32170113, 2020).
myeloproliferative neoplasm (3 papers, 2020 to 2022). A clonal hematopoietic stem cell disorder, characterized by proliferation in the bone marrow of one or more of the myeloid (i.e., granulocytic, erythroid, megakaryocytic, and mast cell) lineages. "A recent study found that HDAC11 can promote the malignant phenotypes of JAK2-driven myeloproliferative neoplasms." (PMID 34395273, 2021). "Inhibitor studies in mouse models showed that HDAC11 plays an important role in oncogene-induced hematopoiesis in myeloproliferative neoplasms (MPNs)." (PMID 32719718, 2020). "Recently, HDAC11 was shown to be important for the proliferation of oncogenic JAK2-driven myeloproliferative neoplasms, and downregulation of HDAC11 expression could promote apoptosis in human leukaemia." (PMID 34395273, 2021). "Selective/class-specific inhibitors targeting HDAC11 have been developed for treating patients with myeloproliferative neoplasms (MPN)." (PMID 32719718, 2020).
myocarditis (3 papers, 2022 to 2025). Myocarditis is a condition that is characterized by inflammation of the heart muscle (myocardium). "While previous studies have linked HDAC11 to brain degeneration, chronic muscle metabolic disease, myocarditis, and various tumors, its role in kidney diseases has been less explored." (PMID 41275091, 2025). "It has been reported that reconstitution of HDAC11 reduced IL-13 expression, while inhibition of HDAC11 increased IL-13 expression in CD4+ T cells of heart tissue in patients with myocarditis." (PMID 35279683, 2022).
ovarian carcinoma (3 papers, 2022 to 2024). A malignant neoplasm originating from the surface ovarian epithelium. "It has been reported that the loss of HDAC11 in ovarian cancer cells can inhibit the metabolic activity of cells and induce cell death." (PMID 37894746, 2023). "In addition, the Cancer Genome Atlas shows that HDAC11 promoter methylation is associated with a poor prognosis of ovarian cancer patients, suggesting the need for in-depth studies of the specific mechanisms of HDAC11 in specific tumors." (PMID 38536720, 2024). "It has been reported that the deletion of HDAC11 leads to cell death in colon, prostate, breast, and ovarian cancer cell lines." (PMID 35252174, 2022). "However, the role of HDAC11 in ovarian cancer metastasis has been rarely reported." (PMID 37894746, 2023). "As the double-edged roles of HDAC11, and the little evidence in ovarian cancer treatment, furthermore in-depth studies about HDAC11 should be taken into consideration." (PMID 35252174, 2022).
age-related macular degeneration (2 papers, 2024 to 2025). Age-related loss of vision in the central portion of the retina (macula), secondary to retinal degeneration. "Decreased chromatin accessibility has been identified as a characteristic feature in retinal diseases, mostly in age-related macular degeneration, and HDAC11 in particular has been proposed as a therapeutic target." (PMID 39389360, 2024). "Conversely, in fibroblasts, HDAC11 overexpression inhibited cell cycle progression in both transformed and non-transformed fibroblasts, while in age-related macular degeneration, HDAC11 overexpression reduced chromatin accessibility." (PMID 40427555, 2025).
asthma (2 papers, 2025). "In asthma, the E3 ubiquitin ligase March1 promotes the expression of OX40L in allergen-stimulated dendritic cells by mediating the ubiquitination of HDAC11." (PMID 40413536, 2025).
colon carcinoma (2 papers, 2021 to 2022). "It suggested that the expression levels of HDAC11 might be related to metastatic potential of colon cancer cells." (PMID 35399729, 2022). "Moreover, qRT-PCR analysis was used to verify HDAC11 expression levels within the colon cancer cell lines." (PMID 35399729, 2022).
epilepsy (2 papers, 2019 to 2022). A brain disorder characterized by episodes of abnormally increased neuronal discharge resulting in transient episodes of sensory or motor neurological dysfunction, or psychic dysfunction. "At several epilepsy-related genes, like HDAC11, SPP1, GAL, DRD1 and SV2C, significant differential methylation and differential gene expression coincided." (PMID 31887157, 2019).
graft versus host disease (2 papers, 2016 to 2021). An immune system disorder that occurs after allogeneic hematopoietic stem cell transplant and is a reaction of donor immune cells against host tissues. "HDAC11 is the newest member of the histone deacetylase family and has been reported to involve in hematopoietic lineage differentiation, as well as graft versus host disease (GVHD)." (PMID 27458169, 2016).
leukaemia (2 papers, 2014 to 2021). "To investigate the significance of Class I HDACs (HDAC1, HDAC2, HDAC3, and HDAC8), HDAC11, and Klfs (Klf1, KLf3, Klf4, and Klf7) in the pathogenesis of human leukemia, we used real-time RT-PCR to evaluate the expression of HDACs and Klfs in bone marrow samples from human leukemia patients." (PMID 25341045, 2014).
lymph node metastasis (2 papers, 2022 to 2023). "They observed a correlation between decreased HDAC11 levels and advanced clinical stage as well as lymph node metastasis in CRC patients." (PMID 37511338, 2023).
lymphoma (2 papers, 2014 to 2021). A malignant (clonal) proliferation of B- lymphocytes or T- lymphocytes which involves the lymph nodes, bone marrow and/or extranodal sites. "Tumor growth rates of murine lymphoma (EL4) and pancreatic adenocarcinoma cell lines (Panco) were significantly higher in HDAC11 knock out C57BL/6 mice, and myeloid-derived suppressor cells (MDSCs) isolated from HDAC11 knock out mice seem more suppressive than the WT MDSCs." (PMID 34696786, 2021).
medulloblastoma (2 papers, 2013 to 2022). A malignant, invasive embryonal neoplasm arising from the cerebellum. "Interestingly, HDAC11 protein and mRNA levels were reduced drastically in Smo/Smo medulloblastoma." (PMID 23951168, 2013).
multiple sclerosis (2 papers, 2014 to 2018). A progressive autoimmune disorder affecting the central nervous system resulting in demyelination. "As with the SIRT4 and SIRT5 genes, variants in HDAC11 were also shown to influence multiple sclerosis in terms of brain volume." (PMID 25322459, 2014). "Genetic variability in HDAC9, along with variants in HDAC11, SIRT4 and SIRT5, has also been shown to influence brain volume in multiple sclerosis (MS) patients, as assessed used neuroimaging methods." (PMID 25322459, 2014). "In an animal model for multiple sclerosis, the absence of HDAC11 reduces clinical severity, spinal cord demyelination, and immune cell infiltration, suggesting that HDAC11 is a promising target for MS treatment." (PMID 30456376, 2018).
sarcopenia (2 papers, 2023 to 2025). Progressive decline in muscle mass due to aging which results in decreased functional capacity of muscles. "Conversely, NaB deficiency accelerates the epigenetic pathway mediated by HDAC11 described previously, causing sarcopenia." (PMID 37881635, 2023). "For example, binding of HDAC11 to Myo D can reduce Myo D-dependent histone acetylation near the promoter of the myostatin gene, thus repressing its transcription and causing sarcopenia." (PMID 37881635, 2023). "Here we have shown for the first time the consequences of HDAC11-deficiency in sarcopenia." (PMID 40220154, 2025). "And the upregulation of HDAC11 expression facilitates its binding to Myo D, which cooperates with epigenetic alterations to promote the development of sarcopenia." (PMID 37881635, 2023). "Altogether, our results highlight HDAC11 as a novel target for the treatment of sarcopenia." (PMID 40220154, 2025). "Taken together, our results point to HDAC11 as a new target for the treatment of sarcopenia." (PMID 40220154, 2025).
age (1 paper, 2025). A temporal measurement of the time period elapsed since an identifiable point in the life cycle of an organism. "This study focuses on the critical role of HDAC11 in age-related hearing loss and its underlying mechanisms." (PMID 40667486, 2025).
alcoholic liver diseases (1 paper, 2021). A disorder caused by damage to the liver parenchyma due to alcohol consumption. "In addition, histone deacetylase 11 (HDAC11) is induced in Kupffer cells of alcoholic liver disease model mice, which reduces the expression of IL-10." (PMID 34276405, 2021).
alcoholism (1 paper, 2022). "Interestingly, the GO term “alcoholism” was enriched in genes associated with the “CGI-free intergenic UMR” category, including Shc3, Shc4, Araf, Fosb, Hdac11, Adcy5, Creb3l2, Gnai2, Grin2d, and Ppp1r1b." (PMID 35205351, 2022).
Allergy (1 paper, 2023). An allergy is an immune response or reaction to substances that are usually not harmful. "The findings indicated an increase in the expression of allergy-related genes in the nasal mucosa, CD23 expression during T-B cell interaction, and TNF-induced HDAC11 expression." (PMID 37692890, 2023).
anaplastic oligoastrocytoma (1 paper, 2021). An oligoastrocytoma characterized by the presence of increased cellularity, nuclear atypia, pleomorphism, and high mitotic activity. "HDAC11 displayed 4.20-fold downregulation in anaplastic oligoastrocytoma (n = 4) (p = 1.09E-05), and 3.93-fold downregulation in anaplastic oligodendroglioma (n = 23) in the French 2005 study (p = 7.32E-06)." (PMID 34540896, 2021).
arteriosclerosis (1 paper, 2017). A vascular disorder characterized by thickening and hardening of the walls of the arteries. "Likewise, compared to WT recipients, conditional deletion of HDAC11 within Tregs led to long-term survival of fully MHC-mismatched cardiac allografts, and prevented development of transplant arteriosclerosis in an MHC class II-mismatched allograft model." (PMID 28819166, 2017).
ataxia syndrome (1 paper, 2022). "The study found that the highest expression of HDAC11 was observed in the granule cell layer and Purkinje neurons in the adult rat brain, leading to the conclusion that HDAC11 plays a significant role in ataxia syndrome (lack of coordination of voluntary movements) and locomotor activity." (PMID 35651655, 2022).
bladder (1 paper, 2019). "HDAC10 had a low score for TFBSs associated with muscle tissue, while HDAC11 had a high score for TFBSs associated with the gall bladder." (PMID 31351464, 2019).
bladder cancer (1 paper, 2019). "Again, examination of several bladder cancer cell lines, being typified by distinct malignancy grades and stages, revealed varying patterns of HDAC11 gene activity, with 10/18 lines carrying decreased, 5/18 unchanged and 3/18 elevated mRNA levels." (PMID 30875794, 2019). "Similarly to other histone deacetylases, HDAC11 transcriptional expression may be critically controlled by specific oncogenic networks differentially operating in each bladder cancer cell line examined." (PMID 30875794, 2019).
chromophobe carcinoma (1 paper, 2021). "For example, in RCC (including chromophobe carcinoma, ccRCC, and papillary cell carcinoma), low expression of HDAC1, HDAC2, HDAC3, HDAC8, HDAC10 and high expression of HDAC5, HDAC7, HDAC11 have longer survival time." (PMID 34308568, 2021).
colitis (1 paper, 2022). Inflammation of the colon. "In the current study, we found that the expression of HDAC11 is decreased in mouse colitis tissues and colitis-associated cancer (CAC) tissue compared with normal colon tissue." (PMID 35399729, 2022). "To confirm the finding, we further analyzed the mRNA expression levels of Hdac11 and Mmp3 in the same mouse model (including colitis, CAC and normal colon tissues)." (PMID 35399729, 2022). "In the current study, we found that HDAC11 expression level is lower in mouse colitis tissues and CAC tissue than in normal colon tissue." (PMID 35399729, 2022).
demyelinating disease (1 paper, 2018). A broad group of disorders that affect the myelin sheaths that cover the neurons. "Our results reveal a novel pathophysiological function for HDAC11 in CNS demyelinating diseases, and warrant further investigations into the potential use of HDAC11-specific inhibitors for the treatment of chronic progressive MS." (PMID 30456376, 2018). "To test our hypothesis that HDAC11 is involved in the development or progression of CNS demyelinating diseases, we immunized WT and HDAC11 KO C57BL/6 mice with MOG35–55 to induce EAE." (PMID 30456376, 2018).